IGFLR1 (IGF like family receptor 1)
Description:
Probable cell membrane receptor for the IGF-like family proteins. Binds IGFL1 and IGFL3 with a higher affinity. May also bind IGFL2.
Synonyms: TMEM149; FLJ22573; formerly U2AF1L4
Tractability: Antibody: UniProt places it where antibodies can reach, with high confidence; its Gene Ontology location is reachable by antibodies, with high confidence; UniProt predicts a signal peptide or a membrane-spanning region. PROTAC: its protein half-life has been measured.
Target class: Membrane receptor
Gene: Protein-coding gene on chromosome 19 (35,738,798 to 35,742,455, reverse strand). Ensembl gene ENSG00000126246.
Subcellular location: Cell membrane
Subcellular location (Human Protein Atlas): Nucleoplasm; Plasma membrane
Gene Ontology:
Molecular function: protein binding
Cellular component: plasma membrane
Genetic constraint (gnomAD): Loss-of-function variants: 18 observed, 24.94 expected, observed/expected ratio (o/e) 0.72, 90% interval 0.5 to 1.07. The synonymous counts are far from expectation, so gnomAD's model fits this gene poorly and the ratio says little. Missense variants: 556 observed, 478.55 expected, observed/expected ratio (o/e) 1.16, 90% interval 1.08 to 1.25. Synonymous variants: 265 observed, 215.9 expected, observed/expected ratio (o/e) 1.23, 90% interval 1.11 to 1.36.
Homologues: Orthologues: chimpanzee IGFLR1 (99% identical), macaque IGFLR1 (92% identical), dog IGFLR1 (65% identical), rabbit IGFLR1 (63% identical), mouse Igflr1 (57% identical), guinea pig IGFLR1 (56% identical), rat Igflr1 (56% identical), zebrafish igflr1 (21% identical).
Diseases named in the same sentence as IGFLR1 in open-access papers:
IGFLR1 is named in the same sentence as 26 diseases in open-access papers, as found by Europe PMC text mining. Sharing a sentence is not in itself a finding about the gene and the disease. The quoted sentences say what the papers report.
colorectal cancer (2 papers, 2014 to 2020). A primary or metastatic malignant neoplasm that affects the colon or rectum. "Although the remaining 7 genes (PKD1, FAM38A, WDR81, TMEM136, SLC36A1, SLC26A6, IGFLR1) are mutated in >10% of the colorectal cancer cell lines, literature searches did not reveal evidence of the functional role or therapeutic potential of these genes in colorectal cancer." (PMID 25193853, 2014). "Ren and Zhang (2019) measured scRNA-seq in colorectal cancer, hepatocellular carcinoma and non-small cell lung cancer and found that IGFLR1 may be a tumor immune-related molecule." (PMID 33324675, 2020).
psoriasis (2 papers, 2021 to 2023). An autoimmune condition characterized by red, well-delineated plaques with silvery scales that are usually on the extensor surfaces and scalp. "It is known to be induced by TNFα, but not other psoriasis-associated cytokines, and has been shown to bind with high affinity to the tumor necrosis factor receptor family member TMEM149 (renamed Igflr1)." (PMID 34445339, 2021).
asthma (1 paper, 2024). "As LAYN and IGFLR1 appear to play a role in the immune response of asthmatic patient-derived ILC2s, these genes could also have the potential to be valuable targets for the treatment of asthma." (PMID 39052598, 2024).
Clear Cell Renal Cell Cancer (1 paper, 2020). "Insulin Growth Factor-Like receptor 1 (IGFLR1) reflects progressive disease and confers a poor prognosis in clear cell renal cell cancer (ccRCC)." (PMID 33324675, 2020).
lymph node metastasis (1 paper, 2020). "With the progression of pathological stage and histological grade and lymph node metastasis of ccRCC, the methylation level of IGFLR1 promoter decreased." (PMID 33324675, 2020).
non-small cell lung carcinoma (1 paper, 2020). A group of at least three distinct histological types of lung cancer, including non-small cell squamous cell carcinoma, adenocarcinoma, and large cell carcinoma. "Besides, it has been previously reported that IGFLR1 expression was closely related to immune infiltration of CRC, LIHC and non-small cell lung cancer." (PMID 33324675, 2020).
tumor (6 papers, 2019 to 2026). "We attempted to apply the results of this study to clinical practice, so we not only established a prognostic risk model, but also explored the correlation between IGFLR1 and tumor resistance." (PMID 33324675, 2020). "IGFLR1 may play an important role in tumor related immune infiltration and showed potential diagnostic, therapeutic and prognostic value in ccRCC." (PMID 33324675, 2020). "Therefore, IGFLR1 may play an important role in tumor related immune infiltration and showed potential diagnostic, therapeutic and prognostic value in ccRCC." (PMID 33324675, 2020). "The reason for the difference in IGFLR1 expression level in tumor samples deserved further in-depth and extensive research." (PMID 33324675, 2020). "IGFLR1 promoter methylation level was not only significantly lower in primary tumor than in normal tissues of kidney (0.891 vs. 0.83, p < 0.001), but also revealed a strong correlation with clinical prognosis of ccRCC." (PMID 33324675, 2020). "According to the median expression level of IGFLR1 in ccRCC, the tumor samples were divided into two groups and analyzed the differentially expressed genes (DEGs) in the two groups by “limma” R package, and the results were visualized with volcano plot." (PMID 33324675, 2020). "Subsequently, we investigated the correlation between IGFLR1 and tumor-infiltrating immune cells with the aid of TIMER (Tumor Immune Estimation Resource)." (PMID 33324675, 2020). "IGF-like family receptor 1 (IGFLR1 or TMEM149) seems to relate to tumor-immune cell infiltration." (PMID 41596760, 2026). "Furthermore, to explore the role of IGFLR1 in tumor immunity, we analyzed the correlation between IGFLR1 and infiltration of TIICs and the immune-related signaling pathways through correlation analysis and GSEA." (PMID 33324675, 2020). "In addition, the expression levels of IGFLR1 in ccRCC tumor tissues from TCGA with different histological grade and pathological T, N, M, and stage were compared, subsequently visualized as box plots." (PMID 33324675, 2020). "Therefore, our study provided the reference for elucidating the potential role of IGFLR1 in tumor immunology and its potential application as a biomarker for ccRCC." (PMID 33324675, 2020). "However, the potential function and prognostic value of IGFLR1 in tumor progression and tumor immunology remained unclear." (PMID 33324675, 2020). "As for the prognostic value of IGFLR1, firstly, box plot showed that in RCC patients, the later tumor stage, the higher IGFLR1 expression level was." (PMID 33324675, 2020). "In a cancer context, the high levels of β1, 6-branched N-glycans destabilizes cell adhesion and favors the activation of IGFLR1 mediated signaling, thus increasing the downstream AKT signaling and promote tumor progression." (PMID 31263775, 2019). "Similarly, after adjusting for correlation by tumor purity in TIMER, IGFLR1 expression level was significantly correlated with CD33 (partial cor = 0.61, p < 0.001) and CD11b (partial cor = 0.499, p < 0.001) in ccRCC." (PMID 33324675, 2020).
cancer (4 papers, 2019 to 2024). A tumor composed of atypical neoplastic, often pleomorphic cells that invade other tissues. "Proteins with receptor activity include IGF-like family receptor 1, which is implicated in T-cell-mediated inflammation and associated with the prognosis of various cancers correlating with immune cell infiltration." (PMID 35629968, 2022). "The results showed that upregulated IGFLR1 was detected in ccRCC compared with para-cancer tissues and significantly affected the prognosis of ccRCC (overall survival: Logrank p < 0.0001; disease free survival: Logrank p = 0.022)." (PMID 33324675, 2020). "We analyzed the expression level of IGFLR1 in cancer and para-cancer tissue through “Gene Summary” module in Oncomine and “Differential Expression” module in TIMER." (PMID 33324675, 2020). "Although studies have shown that high expression level of IGFLR1 could predict poor survival among patients with ccRCC, the mechanism of the cancer-promoting effect of IGFLR1 has been still unclear, and previous studies were limited to carbohydrate metabolism." (PMID 33324675, 2020). "IGFLR1 may be related to the regulatory activation, intercellular adhesion of lymphocytes and drug resistance in cancer." (PMID 33324675, 2020). "The results of the present analysis showed that IGFLR1 was significantly correlated with resistance of multiple chemotherapy drugs, including 5-FU, which could help clinicians select effective drugs for individual cancer patient." (PMID 33324675, 2020). "Some upregulated genes of this study were previously identified as potential targets for cancer therapeutics (LAYN, IGFLR1)." (PMID 39052598, 2024). "In the present study, we analyzed the expression level in cancer and para-cancer tissues, and investigated the differences in promoter methylation and copy number variation (CNV) of IGFLR1 in ccRCC whereafter." (PMID 33324675, 2020).
inflammation (1 paper, 2024). Aberrant reaction of the microcirculation characterized by movement of fluid and leukocytes from the blood into extravascular tissues. "Common upregulated genes were e.g. important for T cell immunobiology (ARG2, SLC43A2, IGFLR1), involved in cell migration (LAYN) or known to be involved in cigarette smoke-induced pulmonary inflammation and autophagy in mice (EPHX2)." (PMID 39052598, 2024).
IGFLR1 also shares sentences with these, for which no sentence is quoted: breast carcinoma (1 paper); breast invasive carcinoma (1); central nervous system cancer (1); colon adenocarcinoma (1); colorectal tumors (1); head and neck squamous cell carcinoma (1); kidney cancer (1); kidney chromophobe (1); leukaemia (1); lung adenocarcinoma (1); lung squamous cell carcinoma (1); osteoporosis (1); Pan (1); prostate adenocarcinoma (1); rectum adenocarcinoma (1); thyroid carcinoma (1); uterine corpus endometrial carcinoma (1).